MIR521-2 (microRNA 521-2)
Synonyms: hsa-mir-521-2; MIRN521-2; mir-521-2
Gene: MicroRNA gene on chromosome 19 (53,716,594 to 53,716,680, forward strand). Ensembl gene ENSG00000207549.
Gene Ontology:
Biological process: miRNA-mediated post-transcriptional gene silencing